CLSTN1 (calsyntenin 1)
Description:
Postsynaptic adhesion molecule that binds to presynaptic neurexins to mediate both excitatory and inhibitory synapse formation (By similarity). Promotes synapse development by acting as a cell adhesion molecule at the postsynaptic membrane, which associates with neurexin-alpha at the presynaptic membrane (By similarity). Also functions as a cargo in axonal anterograde transport by acting as a molecular adapter that promotes KLC1 association with vesicles. Complex formation with APBA2 and APP, stabilizes APP metabolism and enhances APBA2-mediated suppression of beta-APP40 secretion, due to the retardation of intracellular APP maturation. [Soluble Alc-alpha]: As intracellular fragment AlcICD, suppresses APBB1-dependent transactivation stimulated by APP C-terminal intracellular fragment (AICD), most probably by competing with AICD for APBB1-binding. [CTF1-alpha]: In complex with APBA2 and C99, a C-terminal APP fragment, abolishes C99 interaction with PSEN1 and thus APP C99 cleavage by gamma-secretase, most probably through stabilization of the direct interaction between APBA2 and APP.
Synonyms: Alc-alpha; KIAA0911; CSTN1; CDHR12; CST-1; XB31alpha; alcalpha1; alcalpha2
Tractability: Antibody: UniProt places it where antibodies can reach, with medium confidence; UniProt predicts a signal peptide or a membrane-spanning region; its Gene Ontology location is reachable by antibodies, with medium confidence. PROTAC: ubiquitination databases record sites on it; its protein half-life has been measured.
Gene: Protein-coding gene on chromosome 1 (9,728,926 to 9,823,993, reverse strand). Ensembl gene ENSG00000171603.
Subcellular location: Postsynaptic cell membrane; Endoplasmic reticulum membrane; Golgi apparatus membrane; Cell projection, neuron projection; Nucleus (Soluble Alc-alpha)
Gene Ontology:
Molecular function: amyloid-beta binding; kinesin binding; protein binding; X11-like protein binding; cell-cell adhesion mediator activity; calcium ion binding
Biological process: cell adhesion; homophilic cell-cell adhesion; positive regulation of synapse assembly; positive regulation of synaptic transmission
Cellular component: endoplasmic reticulum membrane; Golgi membrane; nucleus; cell surface; postsynaptic density membrane; postsynaptic membrane; membrane; neuron projection
Genetic constraint (gnomAD): Loss-of-function variants: 26 observed, 105.69 expected, observed/expected ratio (o/e) 0.25, 90% interval 0.18 to 0.34. The upper end of that interval is the gene's LOEUF score, 0.34, which puts it in group 1 of 6, group 1 being the genes least tolerant of losing a copy. Missense variants: 1,142 observed, 1,320.9 expected, observed/expected ratio (o/e) 0.86, 90% interval 0.82 to 0.91. Synonymous variants: 516 observed, 542.34 expected, observed/expected ratio (o/e) 0.95, 90% interval 0.88 to 1.02.
Homologues: Orthologues: chimpanzee CLSTN1 (99% identical), rat Clstn1 (93% identical), mouse Clstn1 (92% identical), macaque CLSTN1 (91% identical), guinea pig CLSTN1 (90% identical), rabbit CLSTN1 (86% identical), pig CLSTN1 (85% identical), dog CLSTN1 (85% identical), zebrafish clstn1 (74% identical), tropical clawed frog clstn1 (68% identical), Drosophila melanogaster Cals (31% identical), Caenorhabditis elegans casy-1 (30% identical). Paralogues in human: CLSTN2 (53% identical), CLSTN3 (50% identical).
Diseases named in the same sentence as CLSTN1 in open-access papers:
CLSTN1 is named in the same sentence as 45 diseases in open-access papers, as found by Europe PMC text mining. Sharing a sentence is not in itself a finding about the gene and the disease. The quoted sentences say what the papers report.
Alzheimer disease (6 papers, 2013 to 2024). A progressive, neurodegenerative disease characterized by loss of function and death of nerve cells in several areas of the brain leading to loss of cognitive function such as memory and language. "Interestingly, calsyntenin-1 levels are reduced in Alzheimer’s disease brains and this suggests that calsyntenin-1 loss contributes to damaged APP transport in Alzheimer’s disease." (PMID 31806024, 2019). "Biochemical and cell biological studies indicate that Clstn1 could affect degeneration of neural function by influencing Aβ levels in patients suffering from Alzheimer’s disease." (PMID 28912692, 2017). "Thus, defective axonal transport of APP in Alzheimer's disease may be more closely linked to defects in calsyntenin-1 rather than JIP1 mediated cargo transport." (PMID 23825109, 2013). "Studies have shown CSF proteome changes similar to Alzheimer's disease during chemotherapy, including increases in Apolipoprotein E (APOE) and Calsyntenin-1 (CLSTN1), and decreases in Sodium/potassium-transporting ATPase subunit alpha-3 (ATP1A3), linked to several neurological disorders." (PMID 38350915, 2024).
breast carcinoma (6 papers, 2010 to 2024). "This is consistent with the previous study reported that splice isoform switching of CLSTN1 is crucial for EMT in breast cancer." (PMID 38114495, 2023). "Additionally, AKAP8-induced calsyntenin 1 (CLSTN1)-S-splicing isoform formation promotes epitheliality in breast cancer cells." (PMID 39682684, 2024). "A CLSTN1 short isoform has been found to inhibit EMT in breast cancer cells." (PMID 35883549, 2022). "Future studies on the role of CLSTN1 splice isoforms in breast cancer metastasis will be necessary to determine whether this splice isoform switch is functionally important for metastasis, as we previously uncovered for the CD44 splice isoform switch." (PMID 31980632, 2020). "Moreover, AKAP8 expression and the alternative splicing of CLSTN1 predict breast cancer patient survival." (PMID 31980632, 2020).
prostate carcinoma (4 papers, 2008 to 2017). A carcinoma that arises from epithelial cells of the prostate gland. "Among epigenetic biomarkers, most reports indicate GSTP1 hypermethylation as the diagnostic marker for prostate cancer; however, NKX2-5, CLSTN1, SPOCK2, SLC16A12, DPYS, and NSE1 also have been reported to be regulated by methylation mechanisms in prostate cancer." (PMID 24213111, 2011). "Based on methylation in primary tumors compared to normal adjacent tissues, NKX2-5, CLSTN1, SPOCK2, SLC16A12, DPYS and NSE1 are candidate biomarkers for prostate cancer (methylation range 50%–85%)." (PMID 18446232, 2008). "Compared to adjacent normal prostate, all 8 genes had significantly higher methylation in prostate cancer by t-test analysis (P<0.001 for NKX2-5; P<0.001 for SPOCK2; P = 0.004 for GALR2; P<0.001 for CLSTN1; P<0.001 for NSE1; P<0.001 for DPYS; P = 0.019 for FOXN4; P<0.001 for SLC16A12)." (PMID 18446232, 2008).
gastric cancer (3 papers, 2023 to 2025). A primary or metastatic malignant neoplasm involving the stomach. "ESRP1-mediated exon 11 skip splicing of CLSTN1 has been implicated as an anti-metastatic mechanism in gastric cancer, whereby the alternatively spliced, shortened CLSTN1 restricts migration and invasion by stabilizing E-cadherin-β-catenin binding." (PMID 39762313, 2025). "We selected CLSTN1 gene based on previous reports suggesting that an increase in the exon-including isoform of CLSTN1 (CLSTN1-L) is associated with metastasis and poor prognosis in breast and gastric cancers." (PMID 38346537, 2024). "In this study, we confirmed that ESRP1, an RNA-binding protein, can inhibit epithelial-mesenchymal transition and metastasis of gastric cancer by promoting alternative splicing of exon 11 of CLSTN1 mRNA." (PMID 38114495, 2023). "Our results highlight the relationship between ESRP1 and gastric cancer metastasis, elucidating a novel CLSTN1-mediated invasion and metastasis mechanism." (PMID 38114495, 2023). "The post-splicing short CLSTN1 inhibits EMT of gastric cancer cells, and binds to β-catenin and stabilizing the cytoskeleton to inhibit invasion and migration of gastric cancer cells." (PMID 38114495, 2023). "In conclusion, our study confirmed that ESRP1 expression and CLSTN1 splicing level were negatively correlated with metastasis of gastric cancer in vitro, in vivo, and in clinical samples." (PMID 38114495, 2023). "Our results show that ESRP1-regulated CLSTN1 exon 11 alternative splicing also plays an important role in the invasion and metastasis of gastric cancer." (PMID 38114495, 2023). "To study the role of CLSTN1 in gastric cancer metastasis, we constructed full-length (CLSTN1-F) and truncated (CLSTN1-S) overexpression plasmids." (PMID 38114495, 2023). "This emphasizes the potential of ESRP1 and CLSTN1 as attractive therapeutic targets in gastric cancer." (PMID 38114495, 2023). "These may be the mechanisms by which ESRP1 inhibits gastric cancer metastasis through alternative splicing of CLSTN1." (PMID 38114495, 2023). "To further investigate whether CLSTN1, a cadherin, is involved in this process, we conducted co-IP experiment and found that endogenous CLSTN1 and β-catenin interact in gastric cancer cells." (PMID 38114495, 2023). "The post-splicing short CLSTN1 stabilizes the Ecadherin/β-catenin binding structure, and promotes β-catenin protein ubiquitination and degradation, thereby inhibiting the migration and invasion of gastric cancer cells." (PMID 38114495, 2023). "We then overexpressed CLSTN1-F or CLSTN1-S in gastric cancer cells to detect whether the truncated and full length CLSTN1 have different affinities to β-catenin." (PMID 38114495, 2023). "Our results demonstrate that ESRP1-mediated CLSTN1 exon 11 splicing can increase Ecadherin expression, thus inhibiting EMT in gastric cancer cells." (PMID 38114495, 2023). "We further designed primers across exon 11 for verification and found that, after overexpression of ESRP1, the truncated product (exon 11 skipping, 103 bp) of CLSTN1 increased, while the full length (exon 11 no skipping, 160 bp) decreased in gastric cancer cells." (PMID 38114495, 2023). "We found that ESRP1 drives CLSTN1 exon 11 splicing, resulting in the spliced CLSTN1 (short CLSTN1), which participates in inhibiting tumor cell EMT and stabilizing Ecadherin/β-catenin adhesive structure, which is an important mechanism for inhibiting gastric cancer metastasis." (PMID 38114495, 2023).
lung adenocarcinoma (3 papers, 2017 to 2025). A carcinoma that arises from the lung and is characterized by the presence of malignant glandular epithelial cells. "A study in whole mice and lung adenocarcinoma cells found that CLSTN1 expression is decreased in response to 4 Gy gamma irradiation." (PMID 39762313, 2025). "We confirmed that CLSTN1, CLU and NGAL were potential serological biomarker for lung adenocarcinoma prognostic and diagnostic." (PMID 29296216, 2017). "In this study, we found CLSTN1 expression level was significantly increased in tissue and serum of 20 patients with lung adenocarcinoma compared with health control." (PMID 29296216, 2017). "Although CLSTN1 was overexpressed in lung adenocarcinoma tissue and released to serum in our finding; however, the molecular mechanisms of CLSTN1 in lung cancer still need to be confirmed in the future." (PMID 29296216, 2017). "Combined with two approaches, three proteins including CLSTN1, CLU and NGAL, were highly correlated with lung adenocarcinoma and selected for further analysis." (PMID 29296216, 2017). "In conclusion, our data suggested that the higher levels of CLSTN1, CLU and NGAL in lung adenocarcinoma cultured medium as well as in serum samples tended to be tumor biomarkers for lung adenocarcinoma diagnosis." (PMID 29296216, 2017). "Combined with proteomics and bioinformatics predication, we are successful to identify CLSTN1, CLU and NGAL as new candidate biomarkers for lung adenocarcinoma." (PMID 29296216, 2017). "Therefore, our results suggested that CLSTN1, CLU and NGAL showed great potential to be candidate biomarkers for lung adenocarcinoma." (PMID 29296216, 2017). "Additionally, we examined expression levels of CLSTN1, CLU and NGAL of serum samples from 20 patients with lung adenocarcinoma and 10 healthy volunteers with age/sex matched." (PMID 29296216, 2017). "Both CLSTN1 and NGAL highly expressed in the cytoplasm of tumor cells in all (12/12) of the lung adenocarcinoma samples, but not in normal alveoli cells." (PMID 29296216, 2017).
lung carcinoma (2 papers, 2017 to 2020). "AS events of KIF1B and CLSTN1 have been reported to be involved in ovarian cancer and lung cancer development." (PMID 32939931, 2020). "We next validated expression level of tumor tissues from lung cancer patients for CLSTN1, CLU and NGAL with immunohistochemistry staining." (PMID 29296216, 2017). "Taken together, CLSTN1, CLU and NGAL were all highly expressed in lung cancer biopsy samples compared with normal tissues." (PMID 29296216, 2017). "The mean intensity±SD for CLSTN1, CLU and NGAL in lung cancer patients were 82.4±17.2, 110.5±23.8 and 63.5±17.7, whereas in healthy controls, the intensity was 11.3±4.1, 49.2±17.6 and 35.5±5.3, respectively." (PMID 29296216, 2017).
melanoma (2 papers, 2021 to 2022). A malignant, usually aggressive tumor composed of atypical, neoplastic melanocytes. "Thus, it would be interesting for future work to determine the effects of the here detected splicing events of CLSTN1 on EMT in melanoma cells." (PMID 35883549, 2022).
ovarian carcinoma (2 papers, 2010 to 2020). A malignant neoplasm originating from the surface ovarian epithelium. "FN1 and CLSTN1 were also reported in another study as being differentially spliced in breast and ovarian cancer versus normal tissue." (PMID 21118496, 2010).
pancreatic cancer (2 papers, 2020 to 2024). "In the present study, depletion of the CLSTN1 short isoform was observed to promote mesenchymal phenotypes in pancreatic cancer." (PMID 38346537, 2024).
Arrhythmia (1 paper, 2024). Any cardiac rhythm other than the normal sinus rhythm. "Additionally, CLSTN1 overexpression exacerbated the DCM-induced arrhythmia and lead to prolonged RR, QRS, JT, and QT intervals, according to ECG detection." (PMID 36350487, 2024).
bladder cancer (1 paper, 2014). "Some splicing events have been reported to be related to bladder cancer using exon arrays, including CD44, CLSTN1 and CTNND1." (PMID 24622401, 2014).
brain tumor (1 paper, 2025). "Herein we addressed the expression, subcellular localization, and function of CLSTN1 in the embryonal brain tumor medulloblastoma and further explored its previously observed regulation by the pro-invasive kinase MAP4K4." (PMID 39762313, 2025). "Together, our study provides novel insights into the subcellular expression and function of CLSTN1 in the context of a malignant brain tumor." (PMID 39762313, 2025).
colon cancer (1 paper, 2017). "The AS of CALD1, COL6A3, FN1, MAST2, LGR5 and ITGB4 were previously validated in colon cancer using RT-PCR24, while CLSTN1, AUP1, CTNND1, CALD1 and COL6A3 were shown to exhibit tumour-specific splice variants in colon, bladder and prostate cancers." (PMID 28592875, 2017).
coronary artery disease (1 paper, 2024). "Based on proteomic analyses and RNA expression profiling, CLSTN1 has previously been identified as a potentially pathogenic gene in ischemic cardiomyopathy and coronary artery disease in human samples." (PMID 36350487, 2024).
deafness (1 paper, 2020). An inherited or acquired condition characterized by the complete loss of the ability to hear from one or both ears. "Some are also involved in diseases such as Alzheimer’s (Clstn1) and deafness (Espn)." (PMID 32116548, 2020).
dementia (1 paper, 2024). Loss of intellectual abilities interfering with an individual's social and occupational functions. "Moreover, the combination of calsyntenin-1 with other synaptic proteins has shown a potential ability to discriminate FTLD subtypes from other type of dementias, such as FTLD TDP-43-subtype from AD and healthy subjects, and GRN/C9orf72 pre-symptomatic mutation carriers from mutation non-carriers." (PMID 39000564, 2024).
heart failure (1 paper, 2024). Inability of the heart to pump blood at an adequate rate to meet tissue metabolic requirements. "Under doxorubicin treatment, CLSTN1 protein-specific overexpression in the heart muscle promoted cardiac chamber enlargement and heart failure, while the knockdown of CLSTN1 reduced doxorubicin-induced cardiomyocyte toxicity in vitro." (PMID 36350487, 2024). "CLSTN1 could, therefore, be a therapeutic target to prevent the development of Dox-induced DCM and heart failure." (PMID 36350487, 2024).
ischemic cardiomyopathy (1 paper, 2024). Ischemic cardiomyopathy is a cardiomyopathy in which a weakness in the muscle of the heart due to inadequate oxygen delivery to the myocardium with coronary artery disease being the most common cause. "Recently, CLSTN1 has been identified as a potential pathogenic gene in ischemic cardiomyopathy." (PMID 36350487, 2024).
learning disabilities (1 paper, 2019). "We propose that reduced CLSTN1 or excessive ICAM5 during brain development leads to aberrations in dendritic spine formation in FXS, which may contribute to neuropathology phenotypes associated with synaptic abnormality, such as learning disabilities." (PMID 31680833, 2019).
lymph node metastasis (1 paper, 2023). "And splicing ratio of CLSTN1 in patients with lymph node metastasis (LNM) was significantly lower than that in the non-LNM patients." (PMID 38114495, 2023).
Obesity (1 paper, 2023). Accumulation of substantial excess body fat. "CLSTN1 is associated with weight and obesity, which are risk factors for ACL rupture development." (PMID 37884875, 2023).
retinal diseases (1 paper, 2023). "Another small cluster of proteins (cluster 4) that suggest the role of neurodegeneration in these retinal diseases are APP and related proteins (e.g., CYTC, CLSTN1, SPP1, APLP2)." (PMID 36875133, 2023).
stomach adenocarcinoma (1 paper, 2023). "Survival analysis of the SpliceSeq and OncoSplicing database show that stomach adenocarcinoma patients with lower PSI (Percent spliced in) of CLSTN1 had a superior overall survival than patients with high PSI." (PMID 38114495, 2023).